IL1B (interleukin 1 beta)
Diseases named in the same sentence as IL1B in open-access papers (continued):
Sharing a sentence is not in itself a finding about the gene and the disease.
cancer (continued). "Recently, high serum levels of IL-1β, IL-6, IL-8, and TNF-α in cancer patients have been linked to CC pathogenesis." (PMID 30513776, 2018). "It indicates that IL-1β derived from UC-MSCs promotes stem cell-like characteristics via regulating secretome of UC-MSCs, instead of playing a direct role in cancer cells." (PMID 29670904, 2018). "Our results show that treatment of A549 cancer cells with 4-HBA induces the transcription of (amongst others) caspase-1, IL1β, and IL18 encoding genes." (PMID 29352134, 2018). "As expected, plasma levels of IL-8, IL-6, TNFα, IL-1β, and G-CSF were all significantly higher in cancer patients compared to healthy individuals." (PMID 29324871, 2018). "When we inhibited miR-146a and miR-181b with anti-miRs, we observed that the TEM of both HT29 and LoVo cancer cells was increased by about two-fold in the presence of IL-1β." (PMID 29402939, 2018). "The role of TLR stimulation (and similarly, IL-1β, which shares the MyD88 signalling pathway) in cancer progression is somewhat contentious and appears to depend on the specific TLR in question." (PMID 29415982, 2018). "IL-1β transcription is regulated by Notch in cancer cells, differently from its regulation in the cells of myeloid lineage, where its expression is stimulated by the engagement of toll-like receptors or endogenous danger signals." (PMID 30154786, 2018). "Human Cytokine Array analysis showed that cancer patients have a significant increase in saliva expression of pro-inflammatory markers IL-1a, IL-1b, IL-6, IL-8, and TNFα compared to controls." (PMID 30018735, 2018). "Similar to cancer cell lines, but less dramatically, mf altered the mRNA expression of IL-1β, CCL13, TGM2 and MMP9." (PMID 29668679, 2018). "The release of PGE2 and its induced cytokines from MSCs is also found to participate in the creation of cancer stem cell niche, the process of which is triggered by Il-1β in TME." (PMID 29670904, 2018). "Cross talk between cancer and stromal cells including Cancer Associated Fibroblast (CAF) is mediated by IL-1β, and several other cytokine cascades." (PMID 29988281, 2018). "It has been shown that fatty acids induce the expression and secretion of inflammatory cytokines such as IL-6, IL-8 and IL-1β via activation of NF-κB pathway in normal and cancer cells." (PMID 30510774, 2018). "IL-1β was shown to increase cancer sphere formation and stem cell marker expressions in colon cancer, while IL-6, IL-8, CCL2 and transforming growth factor-β promoted breast cancer stemness." (PMID 30486830, 2018). "It was recently shown that IL1β induced NO production in cancer cells was responsible for a strong decrease in DKK1 expression, which in turn resulted in the upregulation of WNT/β-catenin signaling." (PMID 29165387, 2017). "IL-1β activates signaling pathways and induces the expression of genes that promote carcinogenesis and cancer progression." (PMID 28881826, 2017). "While serving as pro-senescent compounds in cancer cell models, ginsenoside Rg1 was reported to exhibit protective effects against IL-1β, H2O2, and tert-Butyl hydroperoxide-induced senescence in endothelial progenitor cells and fibroblasts." (PMID 28287423, 2017). "The maintenance of an inflammatory TME is further stabilized through the JAK/STAT and the IKK/NF- χβ pathways, whose effects are robustly sustained by a feedback from cancer cells through the production of inflammatory cytokines such as IL-1β, IL-6 and TNF-α." (PMID 28969664, 2017). "Active caspase-1 p20 was detected in every HNSCC cancer tissue sample, suggesting that IL-1β also has to be cleaved to become activated." (PMID 28430665, 2017). "Pharmacological BTK inhibitors in vivo affected S. aureus clearance in mice and IL-1β release in cancer patients, which was associated with a reduced ability of isolated PBMC to secrete IL-1β." (PMID 29167667, 2017).
cancer (continued). "IPA also identified potential upstream regulators, which play a key role in cancer invasiveness: interleukin-6 (IL-6), IL1B and transforming growth factor, beta-induced (TGFBI) were the top three upstream activated regulators (P< .05)." (PMID 28632775, 2017). "For example, cancer cells stimulate expression of adipokines and adipocytokines (including IL-6, IL-1β, CCL2, CCL5, TNF-α, MCP-1, leptin), proteases, and inhibitors (e.g., MMP-11, PAI-1)." (PMID 28101337, 2017). "A recent study suggest that Lipoxins (LXs) and analogues exert strong analgesic effects on cancer-induced bone pain (CIBP) and suppress the pain associated expression of spinal proinflammatory cytokines (IL-1β and TNF-α)." (PMID 28587280, 2017). "Astrocytes secrete hepatocyte growth factor/scatter factor (HGF/SF) under the influence of cancer cell-derived IL1β." (PMID 29312881, 2017). "MSCs under pathological conditions, such as tissue injury or cancer, are mobilized towards the site of damage attracted by the pro-inflammatory environment, such as increased local or systemic interleukin-1 beta (IL-1β)." (PMID 29262555, 2017). "IL-1β levels strongly associated with subjective (weight loss, loss of appetite) and objective (albumin and CRP levels) measurements of cancer cachexia." (PMID 28177923, 2017). "CXCL1, MMP9, IL1B, WNT7A, and CCL2 were associated with cancer malignant characteristics which were remarkably decreased in Top 10 list." (PMID 28881805, 2017). "In cancer cells, IL1β induced nitric oxide production and that this upregulated WNT/β-catenin signaling by inhibiting DKK1 expression." (PMID 29165387, 2017). "Numerous cytokines have been reported to recruit MDSCs in cancer tissues, such as IL-1β, IL-6, IL-4, macrophage colony-stimulating factor, and granulocyte macrophage colony-stimulating factor." (PMID 29326716, 2017). "Our findings indicate that the stimulation of C/EBPβ expression by IL-1β following muscle injury and in cancer cachexia acts to promote SC survival, and is therefore a protective mechanism for SCs and myoblasts in the face of inflammation." (PMID 26913600, 2016). "The exact in vivo role of IL-1β in the development of chronic inflammation, fibrosis and cancer induced by particles has been reviewed in recent publications." (PMID 27519871, 2016). "Surprisingly, after the stimulation of cells with IL-1β or TNFα, after mitophagy induction or in cancer dependent on KRAS signaling, TBK1 is phosphorylated whereas IRF3 is not." (PMID 27538435, 2016). "The activated AIM2 inflammasome in macrophages promotes the proteolytic cleavage and secretion of pro-inflammatory cytokines (IL-1β and IL-18) through the activation of caspase-1, leading to cell senescence, apoptosis and preventing cancer progression." (PMID 27806724, 2016). "Although these processes are important for host defense mechanisms, higher levels of IL-1β is deleterious as shown in several diseases including cancer." (PMID 27538513, 2016). "Most importantly, drugs targeting IL-1β signalling such as anakinra or canakinumab (anti-IL-1β) are approved for treating other diseases and can be adapted to obese cancer patients." (PMID 27708283, 2016). "In various human cancers malignant cells and host infiltrating cells express and secrete a range of Th1, Th2, and Th17 cytokines (IL-1β, IL-2, IL-4, IL-6, IL-10, IL-17, and IFN-γ) and TGF-β." (PMID 27777963, 2016). "The resulting enhancement of the invasion appears to be related to an increased expression of COX-2, since the addition of a COX-2 inhibitor completely prevented the stimulation of cancer cell invasion induced by IL-1β." (PMID 27282478, 2016). "Whereas genes likely to be associated with development of cancer cachexia, such as ADAMTS1, and the key mediator of inflammatory response, such as IL1B, were down-regulated in SP cells." (PMID 27725724, 2016). "One of its ligands, Interleukin-1 beta [IL-1β], is a critical inflammation factor related to poor prognosis and patient survival in cancer." (PMID 26870992, 2016).
cancer (continued). "A better understanding of the intricate roles of IL-1β signaling in the malignant process will facilitate the application of novel IL-1β modulator in cancer patients." (PMID 27057094, 2016). "Various chemotherapeutic agents can cause ATP release from cancer cells, which in turn activates P2X7 in a paracrine manner to mediate IL-1β release from antigen presenting cells to promote antitumor immunity." (PMID 27524862, 2016). "Thereby, ligand-activation of GPER generates a feedforward loop coupling IL1β induction by CAFs to IL1R1 expression by cancer cells, promoting the up-regulation of IL1β/IL1R1 target genes such as PTGES, COX2, RAGE and ABCG2." (PMID 27072893, 2016). "Clinically, the measurement of IL-1β, IL-18, IL-6, and MIC-1/GDF-15 correlates with the risk of carcinoma and the prognosis of established cancer." (PMID 27429614, 2016). "Here, we show that ligand-activated GPER triggers the EGFR/ERK/PKC signal transduction pathway generating a feedforward loop that couples IL1β induction by CAFs to IL1R1 expression by cancer cells." (PMID 27072893, 2016). "Other studies also reported that antioxidants dose-dependently inhibit inflammatory markers like TNF- α and IL-1β in in vitro studies and their release from a human cancer cell line." (PMID 26262605, 2015). "Serum TNF-α and IL-6 in the severe cancer group were higher than those in control, whereas serum IL-1β leveled off in all groups." (PMID 25797259, 2015). "For instance, il1b, which promotes early cancer angiogenesis, was significantly upregulated while anti-tumor cytokines, il4, il6, il8, il10, il12, and tnfa, all showed significant downregulation." (PMID 25828472, 2015). "In this cancer-promoting process, IL-1β and CXCL1-CXCR2 have crucial regulating roles in integrating inflammation stimuli and an EGFR signaling cascade." (PMID 26462152, 2015). "Stomach-specific expression of human IL-1β in transgenic mice leads to spontaneous gastric inflammation and cancer that correlates with early recruitment of myeloid-derived suppressor cells (MDSCs) to the stomach." (PMID 26176534, 2015). "Further, our findings show that soluble IL-1β, secreted by TNBC cells, is responsible for inhibiting asporin in normal and cancer-associated fibroblasts." (PMID 26327350, 2015). "Many studies have demonstrated that in response to paclitaxel administration, cancer cells up-regulate inflammatory mediators such as IL-1β, IL-6, IL-8, and VEGF-A, which also facilitate angiogenic activity." (PMID 26015406, 2015). "These cells can be generated in the bone marrow in response to factors such as IL-6, GM-CSF, IL-1β, TNFα and have been shown to contribute to cancer immune evasion by suppressing T cell functions and promoting activation and expansion of Foxp3+ Tregs cells." (PMID 26109431, 2015). "In mice, an increase in IL-1β in the spinal cord was observed following spinal cord injury, sciatic nerve injury and in cancer pain models and also in the sciatic nerve in the partial sciatic nerve injury." (PMID 26218747, 2015). "It is particularly interesting that studies of pain in cancer patients have shown the importance of cytokine genes including IL6, TNF and IL1B polymorphisms." (PMID 26269716, 2015). "In this study, we show that repetitive oral administration of XAT decoction for a week can greatly suppress the increased IL-1β and TNF-α associated with the cancer pain." (PMID 26617438, 2015). "E7 induces the expression of IL1β, which, in turn activates the expression of NF-κB, a key modulator in the transition of chronic inflammation to cancer." (PMID 25663851, 2015). "The NF-κB pathway plays the most important role in cancer-related inflammation by mediating the DNA transcription of a series of inflammation-related cytokines such as IL-1β." (PMID 26474279, 2015).
cancer (continued). "Collectively, miRNA regulation of the expression of interleukins (IL-11, IL-1β, IL-24 and IL-32) emerges as a useful tool in probing modulatory mechanisms of cancer promotion/suppression and their (in)direct implication in immunotherapeutic approaches." (PMID 25590298, 2015). "In the current study, when hMSCs were co-cultured with IL-1β producing cancer cells, hMSCs became proinflammatory cells and their number declined." (PMID 26204886, 2015). "Our results revealed that in HDC−/− mice, there was marked induction by OVA of a number of MC-derived proinflammatory cytokines, including several key cancer-promoting cytokines such as IL-1β and IL-6 and their downstream effector cytokine IL-17a." (PMID 26429861, 2015). "Our data revealed that the decline in hMSC number occurred when co-cultured with cancer cells expressing high levels of IL-1β." (PMID 26204886, 2015). "Currently, roles of IL-1β and myeloid-derived suppressor cells (MDSCs) in cancer development have drawn much attention." (PMID 25706411, 2015). "Proinflammatory cytokines such as TNF-α and IL1-β are known to regulate ASS expression in some cancer cell lines." (PMID 25333458, 2015). "We also previously reported that NF-κBp65 gene expression is increased in the subcutaneous white adipose tissue of cachectic cancer patients, concomitantly to up-regulation of its inflammatory target genes IL-1β, TNF-α, CCL2/MCP-1, and IκB-α." (PMID 26732354, 2015). "Taken together, these results indicate that immunosuppressive tissue microenvironment built in DJ-1 KO mice can enhance lung migration of cancer, and IL-1β plays an important role in promoting the cancer migration." (PMID 25706411, 2015). "Chemotherapy is known to increase concentrations of proinflammatory cytokines such as TNF-α, IL-6, and IL-1β in cancer patients." (PMID 25945105, 2015). "Concurrently, miRNA regulation of the expression of interleukins (IL-11, IL-1β, IL-24 and IL-32) emerges as a useful tool in probing modulatory mechanisms of cancer promotion/suppression and their (in)direct implication in immunotherapeutic approaches." (PMID 25590298, 2015). "IL-1β has been known to have a wide range of biological activities, not only on recruiting MDSCs, but also directly on various characteristics of cancer cells." (PMID 25706411, 2015). "For example, leucocytes from cancer patients with post-treatment fatigue showed increased expression from both IL-1β and IL-6 genes." (PMID 26469939, 2015). "So far, roles of DJ-1 in regulating IL-1β expression and building inflammatory microenvironment for cancer development are still unclear." (PMID 25706411, 2015). "It is a central enzyme in the inflammatory response, its activity in cancer cells can be directly stimulated by NF-kB after radiation exposure or indirectly through some cytokines activity, such as IL-1β." (PMID 25705130, 2015). "Overall, based on recent studies addressing the roles of TNF-α and IL-1β in malignancy, both cytokines are now considered potential targets for therapy in cancer." (PMID 25928089, 2015). "The MB-downregulated genes include cancer-associated cytokines/chemokines (e.g. CXCL1, CXCL2, CXCL3, CXCL14, IL1A, IL1B, IL6, IL8) and matrix metalloproteinases (MMP1,MMP9)." (PMID 25642713, 2015). "IL-1β is present in the serum and ascites of OC patients and has been shown to be involved with cancer tumorigenesis, angiogenesis, and metastasis." (PMID 25403235, 2014). "from Philippine dairy products on cancer cells and normal fibroblasts and their effects on expression of early apoptotic-promoting cfos, cjun and proinflammatory cytokine IL-1β, TNF-α genes." (PMID 25276792, 2014). "Constitutive activation of NF-κB, the major pathway that regulates immune inflammatory responses and produces pro-inflammatory cytokines, such as TNF-α, IL-1β, and IL-6, leads to chronic inflammation, which promotes cancer." (PMID 24670367, 2014).
cancer (continued). "Related to the gut studies in the first section, IL-1β over-expression in the stomach was shown to induce inflammation and cancer." (PMID 24795727, 2014). "PBMC obtained from the cancer patients showed a decreased IL-1β secretion after 24 h of LPS stimulation compared to PBMC from the AR individuals." (PMID 24466243, 2014). "As expected, some cytokines showed significant differences between healthy donors and pretreated cancer patients (IL-1β, IL-2, IL-6, TNF-α, and MCP-1)." (PMID 24800238, 2014). "Advanced cancer patients had similar numbers of circulating myDC to cancer-free patients and healthy individuals, and secreted similar levels of IL-1β, IL-6, IL-10, IL-12 and IL-23." (PMID 23901045, 2014). "A better understanding of the integrative role of IL-1β signaling pathways in the malignant process will enable the application of novel IL-1β modulation approaches in cancer patients." (PMID 24571667, 2014). "Inflammatory cytokines, including tumor necrosis factor alpha (TNFα), interleukin-1beta (IL-1β) and IL-6, increase the invasive capacity of cancer cells." (PMID 24457902, 2014). "Some inflammatory cytokines are consequent on long-term interplay of immune and cancer cells, such as prostaglandins, IL-1β, IL-6, and IL-13, which can trigger the expansion and activation of MDSCs." (PMID 25937967, 2014). "A few studies have documented constitutive IL-1β protein production in human and animal cancer cell lines, including sarcomas and ovarian cell carcinomas." (PMID 24734023, 2014). "Factors upregulated in the cancer pain state, such as IL-1β, PPD mRNA, dynorphin, GFAP, and substance P were decreased after electroacupuncture treatment." (PMID 25383081, 2014). "IL-1β is also known to promote cancer progression by upregulating pro-metastatic genes such as matrix metalloproteinases and stimulate adjacent cells to produce angiogenic proteins or growth factors including VEGF, IL-8, IL-6, TNF-α and TGF-β." (PMID 23495140, 2013). "Taken together, our data support a model where MSCs contribute to tumorigenicity through their pro-inflammatory phenotype induced by cancer cell-derived factors, such as IL1β." (PMID 24405819, 2013). "Along with IL-1β, the cytokine IL-18 is also cleaved by caspase-1 into its mature form and plays both beneficial and detrimental roles in the progression of cancer." (PMID 24273542, 2013). "Other studies also reported that antioxidants dose-dependently inhibit inflammatory markers like TNF-α, IL-6, and IL1β gene expression in the cells of chronic diseases and their release from a human cancer cell line." (PMID 23365614, 2013). "It is crucial to determine the manner in which EGF-induced IL-1β regulates cancer cells to escape from cisplatin-induced cytotoxicity." (PMID 23383347, 2013). "Taken together, our data suggest that IL-1β contributes to both the invasive ability of cancer cells and to the activation of Notch signalling through astrocytes." (PMID 23495140, 2013). "The NLRP3 inflammasome, a protein complex controlling maturation of important pro-inflammatory cytokines interleukin (IL)-1β and IL-18, is also involved in tumorigenesis and metastasis of various cancers." (PMID 24223129, 2013). "To clarify the role of EGF in the regulation of IL-1β expression, we assessed the gene expression and promoter activity of IL-1β in EGF-treated cancer cell lines, such as TU183, CA922, SCC25, SCC4, and A431 cells." (PMID 23383347, 2013). "Serum TNF-α and IL-6 increased otherwise in the group with severe cancer when compared to those of control, whereas IL-1β still kept steady among groups." (PMID 23349693, 2013). "Recently, direct effects of IL-1β on cancer stem cells (CSCs) or the niche that favors CSC formation were described." (PMID 23847618, 2013). "A number of studies have implicated specific cancer-cell secreted factors in the activation of neighboring fibroblasts, including TGF-β and IL-1β." (PMID 24068959, 2013).